CD44 (CD44 molecule (IN blood group))
Diseases named in the same sentence as CD44 in open-access papers (continued):
Sharing a sentence is not in itself a finding about the gene and the disease.
ulcerative colitis (6 papers, 2021 to 2024). An inflammatory bowel disease involving the mucosal surface of the large intestine and rectum. "The median fluorescence intensity of CD44 on CD44+CD14+ lymphocytes was nearly 2-fold higher in ulcerative colitis patients treated with biological therapy in comparison to the NBT group." (PMID 36010364, 2022). "Median fluorescence intensity (MFI) of CD44 on CD44+CD14+ lymphocytes was higher in ulcerative colitis patients treated with biological therapy compared to NBT." (PMID 36010364, 2022). "In this study, we detected higher CD44 expression in minor CD44+CD14+ lymphocyte subpopulation in biologically treated ulcerative colitis compared to NBT." (PMID 36010364, 2022). "Patients with Crohn’s disease treated with non-biological therapy (NBT) exhibited a lower percentage of anti-inflammatory CD14+CD16++ monocytes, whereas NBT-treated patients with ulcerative colitis had lower expression of CD44 on CD14+CD44+ lymphocytes in comparison to controls, respectively." (PMID 36010364, 2022). "We can speculate that lower CD44 expression in CD44+CD14+ lymphocyte in blood after NBT, found in ulcerative colitis but not in Crohn’s disease, can be due to the higher naive B-cell count in ulcerative colitis." (PMID 36010364, 2022). "After biological treatment, decreased CD44 expression was detected in non-classical monocytes of ulcerative colitis patients, while Crohn’s disease patients’ monocytes were not affected." (PMID 36010364, 2022). "Biological treatment decreased CD44 expression on non-classical monocytes of ulcerative colitis patients, while monocytes in patients with Crohn’s disease were not affected." (PMID 36010364, 2022).
acute kidney injury (5 papers, 2017 to 2026). Sudden and sustained deterioration of the kidney function characterized by decreased glomerular filtration rate, increased serum creatinine or oliguria. "Furthermore, we did not make any attempt to track ADSCs in this study; but some authors have reported that MSC administered systemically migrate to renal tissue in remnant kidney model and acute renal failure, through CD44-Hyaluronic acid." (PMID 29281649, 2017). "As disease progressed from acute kidney injury to CKD, CD44 was detected in crescents, areas of interstitial fibrosis, and on infiltrating immune cells in both the glomerular and tubulo-interstitial compartments suggesting that LN pathogenesis is accompanied by an increase in CD44 expression." (PMID 39411720, 2024). "Some studies have found that vinorelbine protects against cisplatin-induced acute kidney injury (AKI) by activating Nrf2/HO-1 signaling pathway and hindering TLR4-IFN-γ-CD44 cell inflammatory cascade when investigating the molecular mechanism of renal protection against nephrotoxicity." (PMID 35186957, 2021).
allergic disease (5 papers, 2009 to 2017). An immune response that occurs following re-exposure to an innocuous antigen, and that requires the presence of existing antibodies against that antigen. "Using different antigens, Katoh and colleagues have elegantly demonstrated that CD44 is needed in the development of allergy." (PMID 26999446, 2016). "Our findings therefore provide a novel insight into the role of hypoxia in programming DCs primed Th2 responses via a KIF2A/MT1-MMP/CD44 pathway and implicate that hypoxia might be a promising therapeutic approach in allergic diseases." (PMID 26323509, 2015). "This is based largely on evidence that stem cells or CD34+ progenitor cells are recruited to the site of inflammation in allergic diseases, likely through many of the same adhesion and chemokine receptors used for stem cell homing to the bone marrow (PSGL-1, CXCL12, α4β1 integrin, CD44, etc)." (PMID 20066174, 2009).
Burkitt lymphoma (5 papers, 2010 to 2025). A rare form of malignant mature B-cell non-Hodgkin lymphoma. "CHAC1 and CD44 have been suggested to interact with system Xc- and provide a proferroptotic effect in Burkitt’s lymphoma and an antiferroptosis effect in human gastrointestinal cancer, respectively." (PMID 34281531, 2021). "Although no changes in CD44 expression levels are shown during B cell activation by experimental EBV infection, it seems to be differentially associated with EBV-transformed lymphoblastoid cell lines and Burkitt's lymphoma cells biology." (PMID 26527314, 2015).
cardiac hypertrophy (5 papers, 2012 to 2025). "Cd44 induces inflammation in the body circulation, myocardial fibrosis and cardiac hypertrophy through binding to its ligand hyaluronic acid." (PMID 38402404, 2024). "Hyaluronan (HA) and its receptor CD44 are involved in cellular growth and tissue proliferation but have so far been less studied in myocardial hypertrophy." (PMID 22900226, 2012). "We have previously reported on the distribution of HA and CD44 in the heart of newborn and adult rats and showed that there is an increased synthesis of HA and CD44 in an experimental rat model of cardiac hypertrophy, but the relevance of these components in human HCM is unknown." (PMID 22900226, 2012).
chronic kidney disease (5 papers, 2020 to 2025). Impairment of the renal function secondary to chronic kidney damage persisting for three or more months. "Although the pleiotropic effects exerted by CD44 in exosome biogenesis and function in cancer and chronic kidney disease have been investigated, the role of CD44 in exosomes under MI injury is still poorly understood." (PMID 36463112, 2022). "CD44-hyaluronic acid (CD44-HA) interactions are involved in the process of homing of MSCs to the damaged renal tissue and promote renal function repair following acute tubular injury and chronic renal failure." (PMID 32586408, 2020).
Cognitive impairment (5 papers, 2020 to 2024). Abnormal cognition is characterized by deficits in thinking, reasoning, or remembering. "However, whether CD44 participates in the role of sleep deprivation in cognitive impairment remains unclear." (PMID 33329306, 2020). "Our results indicate that sleep deprivation upregulated CD44 expression in hippocampus tissue, and increased BBB permeability, resulting in cognitive impairment." (PMID 33329306, 2020). "Interestingly, cortical CD44 was reported in a subset of astrocytes in FC layers I–II and WM in humans without cognitive impairment, similar to the CHI3L1 distribution observed in the present NCI cases." (PMID 32066474, 2020).
cutaneous melanoma (5 papers, 2012 to 2024). A primary melanoma arising from atypical melanocytes in the skin. "Importantly, we found that coordinate expression of Id1 or Id3 with HA synthases HAS2, HAS3, and CD44 is associated with reduced overall survival of cutaneous melanoma patients." (PMID 30297743, 2018). "Consistently, coordinate expression of Id1 or Id3 with HAS2, HAS3 or CD44 significantly correlated with reduced survival of cutaneous melanoma patients." (PMID 30297743, 2018). "Similarly, in cutaneous melanoma reduced HA and CD44 levels lead to an early tumor relapse and poor survival." (PMID 28086235, 2017). "A human recurrent cutaneous melanoma (RPM) lacking CD44 was resistant to iota toxin over a broad concentration range; however, these same cells following transfection with the CD44 gene importantly became susceptible to these same concentrations of iota toxin." (PMID 23236484, 2012).
cyst (5 papers, 2016 to 2023). A sac-like closed membranous structure that may be empty or contain fluid or amorphous material. "β-catenin demonstrated tumor epithelial structure, CD44 confirmed that the niche of tumor stem cells were β-catenin nuclear positive cells, which were more obvious in the cyst wall than solid body." (PMID 36810626, 2023). "At the later stages, CD44 was de novo expressed by tubular epithelial cells, increased over time and found in each cyst type and independently of the cell shape (flattened, cuboid or columnar)." (PMID 35055068, 2022). "In addition, we found that the SPP1/CD44 interaction pair stood out among the immune–cyst cell interaction pairs; i.e., macrophages and T lymphocytes specifically highly express CD44, which interacts with osteopontin (OPN) encoded by the SPP1 gene expressed by cyst cells." (PMID 37583898, 2023). "In addition to FGFR2/FGF9, we also found that SPP1/CD44 interactions between immune cells, especially macrophages, and cyst cells may play an important role in the induction of cyst cell formation." (PMID 37583898, 2023). "Finally, cyst formation in vehicle-treated animals appeared to be induced by paracrine effects of surrounding CD44-positive LM7 cells, as these cells were not integrated within the cysts themselves." (PMID 37228489, 2023).
diffuse large B-cell lymphoma (5 papers, 2010 to 2023). "In HIV-1-related diffuse large B-cell lymphoma patients, the CD44 levels significantly increased compared with HIV-1-unrelated diffuse large B-cell lymphoma patients (87% vs. 56%)." (PMID 27455335, 2016). "Moreover, we demonstrate that CD44 can serve as a marker of the activated B-cell (ABC) subtype of diffuse large B-cell lymphoma (DLBCL) and that CD44 expression is correlated with overall survival in DLBCL patients." (PMID 36982699, 2023). "For example, CD44v6 expression in diffuse large B-cell lymphoma (DLBCL) correlates with advanced disease stage, and coexpression of any of the CD44 isoforms with RHAMM could identify a subgroup of DLBCL patients with a very poor prognosis independent of the International Prognostic Index537." (PMID 33888679, 2021).
ependymoma (5 papers, 2014 to 2024). A WHO grade II, slow growing tumor of children and young adults, usually located intraventricularly. "In Cd44lo spheroids derived from ependymoma 5, most of the genes showed negligible reaction to HA, except Cd44 and Cd133, with expression levels decreasing 3.3- and 4.0-fold, respectively, p < 0.05." (PMID 38672482, 2024). "To explore the ontogenies of TAM subsets in spinal ependymomas, we employed RNA velocity analysis and identified two different origins of CD44+ TAMs, including both CD14+ monocytes and CX3CR1+ TAMs." (PMID 34824203, 2021). "Here, we discovered the regulatory roles of TEAD1 in CD44+ TAMs, further highlighting its potential application in ependymoma immunotherapy." (PMID 34824203, 2021). "We reason that strategies that inhibit these CD44+ TAM populations might decelerate the progression of ependymomas." (PMID 34824203, 2021). "Analysis of the hallmark angiogenesis pathway in CD44+ TAMs using gene set enrichment analysis (GSEA) revealed a significant enrichment of tumor angiogenesis, suggesting a pro-tumorigenic role in ependymomas." (PMID 34824203, 2021). "Clodronate-loaded and zoledronate acid-loaded liposomes have been applied to deplete TAMs resulted in decreasing tumor angiogenesis and progression in preclinical solid tumor models successfully, which indicate that these treatments could also be used to deplete CD44+ TAMs in spinal ependymoma." (PMID 34824203, 2021). "The ependymoma cells were found positive to Nanog (13%), CD133 (47.5%), CD44 (65.5%), and CXCR4 (89.7%) when compared to an isotype control antibody." (PMID 25144312, 2014). "The ependymoma cells were found positive to OCT3/4 (2.73%), Nanog (0.95%), CD133 (49.93%), CD117 (36.81%), and CD44 (20.39%) when compared to an isotype control antibody." (PMID 25144312, 2014).
epithelial dysplasia (5 papers, 2018 to 2026). "Severe epithelial dysplasia cases showed down-regulated CD44 expression." (PMID 34830890, 2021). "Immunohistochemistry (IHC) was used to identify stem cell biomarkers in tissue samples, most studies demonstrated that higher expression of stem cell markers (CD44, ALDH1, HELLS, TARIF, SOX2, NANOG, and CD147) correlated with severity of epithelial dysplasia." (PMID 41778103, 2026).
esophageal adenocarcinoma (5 papers, 2011 to 2024). A malignant tumor with glandular differentiation arising predominantly from Barrett mucosa in the lower third of the esophagus. "Esophageal adenocarcinoma samples showed an inverse correlation of E-cadherin and CD44 expression in 63 out of 131 samples (48%), with 41 samples having substantial E-cadherin, but no CD44 expression." (PMID 22069487, 2011). "In an in vitro model of starvation with depletion of glucose and serum factors in the esophageal adenocarcinoma cell line SKGT-4, the starvation-responsive increase in expression levels of HSP90 (and HSP70) was associated with the expression of CSC markers, such as CD44, ALDH1A1, and ABCG2." (PMID 32268506, 2020). "One study focusing solely on esophageal adenocarcinomas showed that the chemoresistance was conveyed through alteration of the Wnt/β-catenin pathway and DKK2, CDH1, CD44, MYC, and ABCG2 expression." (PMID 31467538, 2019).
Follicular Thyroid Carcinoma (5 papers, 2015 to 2025). "In addition, FTC-133 follicular thyroid cancer cells exposed to an RPM for 24 h expressed a CD44 mRNA which was significantly up-regulated in adherent cells but not significantly altered in MCS." (PMID 31731625, 2019). "We finally constructed glycolysis risk score (GRS) predictive models based on four targeting genes (ADM, CD44, MKI67 and TYMS), which were highly upregulated in tumor samples, including papillary and follicular thyroid cancers." (PMID 35528004, 2022).
Granuloma (5 papers, 2017 to 2025). A compact, organized collection of mature mononuclear phagocytes, which may be but is not necessarily accompanied by accessory features such as necrosis. "The adhesion molecule CD44 has been detected on lymphocytes in granulomas of both Crohn’s disease and pulmonary sarcoidosis, and suggested to affect their homing and activation, as well as macrophage differentiation." (PMID 28955342, 2017). "CD44 was the most prominent signaling hub in our granulomas." (PMID 40772762, 2025). "Spatial protein analysis showed that granulomas in all diseases expressed CD68, CD11c, CD44, CD127, and PD-L1." (PMID 39373788, 2024).
HIV-1 infection (5 papers, 2007 to 2024). The type species of lentivirus and the etiologic agent of acquired immunodeficiency syndrome (AIDS). "HA is known to interact with CD44 cell surface receptors, and exogenous HA can reduce HIV-1 infection of CD4+ T-cells in a CD44-dependent manner." (PMID 38399244, 2024). "Interestingly, the impact of these proteins on the spread of HIV-1 between T cells is quite varied when they are incorporated into virions; PSGL-1 and CD43 inhibit HIV-1 infection, whereas CD44 enhances the spread of HIV-1 via trans-infection." (PMID 34696365, 2021). "Although it has been long known that CD44 is incorporated into virus particles, the natural functions of HIV-1-incorporated CD44 in HIV-1 infection have not been clear." (PMID 29934525, 2018).
inflammatory breast carcinoma (5 papers, 2016 to 2023). An advanced, invasive breast adenocarcinoma characterized by the presence of distinct changes in the overlying skin. "In inflammatory breast cancer, the CD44+/CD24−/low cancer stem cell subset harbors higher levels of CYP1B1, and 4-OHE2 treatment induces anchorage-independent growth of mammary epithelial cells." (PMID 35292057, 2022). "This is following our previous observation of a co-regulation of CD44 and Sdc-1 in clinical samples of inflammatory breast cancer." (PMID 34070901, 2021). "For example, Sdc-1 expression in inflammatory breast cancer is correlated with CD44, Notch-1, and Notch-3 expression, and siRNA knockdown of Sdc-1 results in a weaker CSC phenotype and reduced expression of Notch-1-4 and Hey1 in inflammatory breast cancer cells." (PMID 33102470, 2020).
larynx cancer (5 papers, 2013 to 2023). A primary or metastatic malignant neoplasm involving the larynx. "A recent study discovered CD44 as a marker which significantly correlates with response to radiotherapy in early stage larynx cancer patients, both at the mRNA and protein levels." (PMID 23947765, 2013).
lipoma (5 papers, 2018 to 2019). A benign, usually painless, well-circumscribed lipomatous tumor composed of adipose tissue. "In the same study up-regulation of CD44 in lipoma tissue was also reported." (PMID 30987193, 2019). "For example, CD44, a transmembrane glycoprotein, important for cell differentiation and involved in cell-cell and cell-matrix interactions, was expressed in human adipose tissue as well as in lipoma-derived cells." (PMID 31640774, 2019). "When checking gene expression of CD44 and CD90, markers present on adipose-derived mesenchymal stem cells, we found gene expression differences in differentiated lipoma cells that were alpelisib-treated compared to controls." (PMID 31627436, 2019).
malignant pleural mesothelioma (5 papers, 2017 to 2022). A malignant neoplasm that arises from mesothelial cells in the pleura and shows a diffuse growth pattern. "The population of ALDH-positive CD44-positive cells was previously linked with cisplatin resistance in malignant pleural mesothelioma cells." (PMID 31443351, 2019). "We observed that 4MU diminishes CD44 expression in both GBM cell lines, which is consistent with a previous report in a malignant pleural mesothelioma model." (PMID 34628469, 2021). "The transcription machinery of YAP1/TAZ and TEA domain transcription factor (TEAD) activates the transcription of CD44 by coupling to the CD44 promoter at TEAD binding sites, thereby encouraging the propagation of malignant pleural mesothelioma (MPM) cell lines." (PMID 33043017, 2020).
mastitis (5 papers, 2020 to 2025). Inflammation of breast tissue during lactation or postpartum due to an obstructed duct or infection. "Second, it could be induced by S. aureus to impair CD44 signaling and the recruitment of immune cells, which leads to mammary tissue injury and chronic inflammation usually observed in mastitis caused by this pathogen." (PMID 34235202, 2021). "We determined the percentage of CD44+ T cells in the αβ or γδ T cells subsets of blood and milk from healthy and subclinical mastitis cows to assess activation of T cells." (PMID 41142813, 2025). "And on this basis we determined the percentages of CD27+ T cells and CD44+ T cells in the αβ or γδ T cells subsets of the healthy and B. contaminans naturally-induced mastitis cows to assessment the differentiation and activation of T cells." (PMID 36960295, 2023). "To investigate the activation of T subsets, we detected the expression of CD44 molecule in the T subsets of cows with mastitis and healthy cows." (PMID 36960295, 2023). "Lower expression of CD44 in neutrophils isolated from mastitis cows in our study has two explanations." (PMID 34235202, 2021). "In addition, we determined the expression of CD44 molecules on T cells subsets from subclinical mastitis and healthy cows to study T cells subsets activation." (PMID 41142813, 2025). "In addition, CD44 expression is significantly higher on neutrophils in both blood and milk during subclinical mastitis compared to clinical mastitis." (PMID 39335302, 2024). "In addition, we determined the expression of CD44 molecule on the T subsets of the mastitis or healthy cows to investigate the activation of T subsets." (PMID 36960295, 2023). "For instance, cell-surface glycoproteins involved in cell-cell interaction, such as CD44, which mediates specific adhesion of bovine blood polymorphonuclears to mammary epithelial cells, could initiate recruitment of inflammatory cells during mastitis." (PMID 32117805, 2020). "It has been shown that CD44 plays an important role in recruiting blood polymorphonuclear neutrophil leukocytes (PMN) into the mammary gland in bovine mastitis and is significantly upregulated during mastitis." (PMID 39335302, 2024). "However, CD44 decreased (p < 0.05), and CD62L remained unchanged in mastitis as compared to healthy cows." (PMID 34235202, 2021).